SLC3A2 (solute carrier family 3 member 2)
Diseases named in the same sentence as SLC3A2 in open-access papers (continued):
Sharing a sentence is not in itself a finding about the gene and the disease.
Sepsis (6 papers, 2022 to 2025). Sepsis is defined as life-threatening organ dysfunction caused by a dysregulated host response to infection. "Another study found that inhibiting Skp2 can promote ferroptosis by enhancing the ubiquitination of SLC3A2, thereby contributing to sepsis-induced acute lung injury." (PMID 40170095, 2025). "In sepsis, inflammatory cytokine storms suppress Skp2 expression, leading to reduced SLC3A2 ubiquitination and disruption of the translocation of cysteine and glutamate." (PMID 39079969, 2024). "We also used a mouse model of sepsis-induced liver failure, and confirmed through qRT-PCR detection that ferroptosis-related genes Hmox1, Slc3a2, Jun and Zfp36 were significantly correlated with sepsis-induced liver failure." (PMID 35923893, 2022). "Therefore, the suppressed expression of Skp2 in sepsis patients hampered SLC3A2 ubiquitination and the translocation of cystine and glutamate, ultimately leading to ferroptosis." (PMID 39079969, 2024). "In general, the conclusions drawn from these reports are consistent with the results in our research, that is, Hmox1, Epas1, Sirt1, Slc3a2, Jun, Plin2 and Zfp36 collectively promote the development of sepsis-induced liver failure by interacting with B cells and NK cells." (PMID 35923893, 2022). "In addition, we constructed a mouse model, and confirmed through H & E staining, TUNEL staining and qRT-PCR that Hmox1, Slc3a2, Jun and Zfp36 were significantly related to sepsis-induced liver failure." (PMID 35923893, 2022). "As a result, Hmox1, Slc3a2, Jun and Zfp36 may become new therapeutic targets for sepsis-induced liver failure in the future." (PMID 35923893, 2022). "The identification of ferroptosis-related genes Hmox1, Slc3a2, Jun and Zfp36 in the present study contribute to our understanding of the molecular mechanism of sepsis-induced liver failure, and provide candidate targets for the diagnosis and treatment of the disease." (PMID 35923893, 2022). "Therefore, we screened the ferroptosis-related genes (Hmox1, Epas1, Sirt1, Slc3a2, Jun, Plin2 and Zfp36) in this study through bioinformatics analysis, and found that these genes were highly expressed in sepsis-induced liver failure model." (PMID 35923893, 2022). "Among all the Skp2-binding proteins, SLC3A2 (also known as CD98hc or 4F2hc), a cell-surface transmembrane protein that functions upstream of ferroptosis, decreased after the onset of sepsis, suggesting that the decrease in SLC3A2 during sepsis may be mediated by Skp2." (PMID 39079969, 2024). "Mir22hg silencing lightened ferroptosis and ferritinophagy in LPS-induced MLE-12 cells and sepsis mouse models, as presented by the downregulated MDA, ROS, Fe2+, NCOA4, and SLC3A2 levels, upregulated GPX4, GSH, and FTH1 levels, along with a decrease in autophagy." (PMID 38842666, 2024). "Sepsis activated the MEK/ERK pathway and inhibited Skp2 expression in the pulmonary epithelium, resulting in a reduction of K48 ubiquitination of solute carrier family 3 member 2 (SLC3A2), thereby impairing its membrane localization and cystine/glutamate exchange function." (PMID 39079969, 2024).
non-small cell lung carcinoma (5 papers, 2016 to 2023). A group of at least three distinct histological types of lung cancer, including non-small cell squamous cell carcinoma, adenocarcinoma, and large cell carcinoma. "Indeed, the non-small cell lung cancers (NSCLCs) of patients showing a short survival rate express the lowest and the highest levels of PTPRJ and SLC3A2, respectively." (PMID 29805737, 2018).
colon adenocarcinoma (4 papers, 2021 to 2025). "We searched TCGA databases, the results indicated that SLC7A11 expression and SLC3A2 expression were obviously enhanced in colon adenocarcinoma (COAD), compared with normal samples." (PMID 41341590, 2025).
oral cancer (4 papers, 2012 to 2024). "Previous studies reported that upregulation of SLC3A2 facilitated cell proliferation and was associated with patient survival and progress in oral cancer." (PMID 35057861, 2022). "Previous studies have indicated that SLC3A2 plays a role in the progression of oral cancer by promoting cell growth and suppressing programmed cell death in individuals." (PMID 39807126, 2024).
osteoarthritis (4 papers, 2022 to 2025). A noninflammatory degenerative joint disease occurring chiefly in older persons, characterized by degeneration of the articular cartilage, hypertrophy of bone at the margins and changes in the synovial membrane. "SLC3A2 also showed potential therapeutic possibility for osteoarthritis, as it inhibited ferroptosis and preventing cartilage degeneration." (PMID 40420260, 2025). "The nomogram model based on biomarkers demonstrates that SLC3A2 and SLC7A5 have potential diagnostic value in osteoarthritis." (PMID 40420260, 2025). "SLC3A2 downregulation promotes chondrocyte ferroptosis in osteoarthritis." (PMID 38438962, 2024).
acute myeloid leukemia (3 papers, 2022 to 2025). Acute myeloid leukemia (AML) is a group of neoplasms arising from precursor cells committed to the myeloid cell-line differentiation. "The results demonstrated that SLC3A2 and SLC7A5 were significantly enriched in ribosome, acute myeloid leukemia, insulin signaling pathway, olfactory transduction, etc.." (PMID 40420260, 2025).
Alzheimer disease (3 papers, 2021 to 2026). A progressive, neurodegenerative disease characterized by loss of function and death of nerve cells in several areas of the brain leading to loss of cognitive function such as memory and language. "In addition, the upstream mRNA expression of SLC7A11 and SLC3A2 was related to β-amyloid expression in transgenic mice and an in vitro model of human Alzheimer’s disease." (PMID 34575878, 2021). "Prior research confirmed that the occurrence of ferroptosis in the Alzheimer’s disease mouse model was accompanied by a significant decrease in SLC7A11, SLC3A2, and FTH1 and an increase in the protein expression of DMT1 and NCOA4." (PMID 39635435, 2024). "In transgenic mice and in vitro models of Alzheimer’s disease, the gene expression of the two system xc− subunits SLC7A11 and SLC3A2 was found to be increased in the presence of β-amyloid." (PMID 34575878, 2021).
atherosclerosis (3 papers, 2023 to 2025). A disease characterized by the build-up of fatty material and calcium deposition in the arterial wall resulting in partial or complete occlusion of the arterial lumen. "SLC3A2, which was found to be associated with ferroptosis and atherosclerosis plaque progression, was decreased in HCM patients." (PMID 39701955, 2024). "Additionally, SLC3A2 is critical for vascular smooth muscle cell (VSMC) proliferation, and its deficiency has been linked to the formation of unstable plaques in atherosclerosis." (PMID 39790063, 2025).
colorectal tumour (3 papers, 2022 to 2023). "SLC3A2 (solute carrier family 3 member 2)/CD98hc (heavy chain) is the target antigen recognized by the SF-25 antibody, which binds to colorectal tumour cells but not normal counterparts." (PMID 36831514, 2023). "In this study, MIF and SLC3A2 were shown to participate in regulating the biological behaviour of colorectal tumour cells and promote the further development of cancer, suggesting that MIF and SLC3A2 might serve as potential biomarkers." (PMID 35567291, 2022).
esophageal cancer (3 papers, 2012 to 2025). A primary or metastatic malignant neoplasm involving the esophagus. "SLC3A2 expression is indispensable for multiple cell lines’ proliferation, especially for ESO51 (a cell line for esophageal cancer)." (PMID 35992269, 2022).
kidney cancer (3 papers, 2022 to 2025). Primary or metastatic malignant neoplasm involving the kidney. "By contrast, excessive methylation of SLC3A2, which reflected suppressed transcription, was associated with poor T cell function in a kidney cancer cohort." (PMID 35992269, 2022).
laryngeal carcinoma (3 papers, 2022 to 2024). Carcinoma that arises from the laryngeal epithelium. "Taken together, our data indicated that SLC3A2 is overexpressed in laryngeal carcinoma and associated with poor survival." (PMID 35057861, 2022). "High SLC3A2 expression is associated with poor survival in laryngeal carcinoma, though there is a reversely result that some patients with higher SLC3A2 displayed longer survival after 3000d." (PMID 35057861, 2022). "In addition, we demonstrated that SLC3A2 deficiency decelerates cell ferroptosis of laryngeal carcinoma." (PMID 35057861, 2022). "SLC3A2 deficiency negatively regulated cell growth and tumorigenesis in laryngeal carcinoma." (PMID 35057861, 2022). "Next, we clarified its underlying mechanism of SLC3A2 in ferroptosis of laryngeal carcinoma cells." (PMID 35057861, 2022). "Mechanically, SLC3A2 deficiency facilitated ferroptosis through upregulating the expression of mTOR and P70S6K, whereas inhibited p-mTOR and p-P70S6K expression in laryngeal carcinoma cells." (PMID 35057861, 2022). "SLC3A2 deficiency upregulated the expression of mTOR and P70S6K, whereas inhibited p-mTOR and p-P70S6K expression in laryngeal carcinoma cells." (PMID 35057861, 2022). "Taken together, our data indicated that SLC3A2 is a suppressor in regulating of ferroptosis in laryngeal carcinoma cells." (PMID 35057861, 2022). "Our study suggests that SLC3A2 regulates ferroptosis and related genes, and therefore subsequently induces laryngeal carcinoma growth and ferroptosis via mTOR signal pathway." (PMID 35057861, 2022). "This study aimed to explore the mRNA and protein expression of SLC3A2 in laryngeal carcinoma cells and tissues, and functional regulatory mechanism of SLC3A2 in cell ferroptosis of laryngeal carcinoma." (PMID 35057861, 2022). "In order to clarify the role of SLC3A2 in laryngeal carcinoma, we first analyzed the expression of SLC3A2 in TCGA dataset." (PMID 35057861, 2022). "Here, we screened out SLC3A2 as a key gene involved in ferroptosis in laryngeal carcinoma by TCGA data analysis." (PMID 35057861, 2022). "We chose the key gene-SLC3A2 of DEGs from TCGA by bioinformatics analysis, and then we constructed stable knockdown of SLC3A2 in laryngeal carcinoma cells." (PMID 35057861, 2022). "In this study, we demonstrated that SLC3A2 as a key component involving ferroptosis, is upregulated in laryngeal carcinoma." (PMID 35057861, 2022). "Collectively, our data suggested that SLC3A2 positively regulates cell viability and foci formation in laryngeal carcinoma cells." (PMID 35057861, 2022). "Our study suggests that SLC3A2 negatively regulates ferroptosis through mTOR pathway in laryngeal carcinoma." (PMID 35057861, 2022). "The expression of SLC3A2 was also upregulated in laryngeal carcinoma cells (HN13 and HN8) compared with normal cells (HOK)." (PMID 35057861, 2022). "SLC3A2 was highly expressed in laryngeal carcinoma compared with normal (p < 0.001), and patients with high SLC3A2 expression showed a poor fraction survival (p = 0.045)." (PMID 35057861, 2022). "Then we examined the cell viability in SLC3A2 knockdown laryngeal carcinoma cell lines by MTT assay." (PMID 35057861, 2022). "Furthermore, we analyzed the mRNA and protein expression of SLC3A2 in laryngeal carcinoma tissues and cells." (PMID 35057861, 2022). "The mechanism of SLC3A2 in laryngeal cancer is currently unclear." (PMID 35057861, 2022). "SLC3A2 is highly expressed in laryngeal carcinoma tissues and cells." (PMID 35057861, 2022). "Moreover, SLC3A2 is a key gene in ferroptosis in laryngeal carcinoma." (PMID 35057861, 2022). "Next, we consider to confirm whether SLC3A2 directly regulates mTOR in laryngeal cancer." (PMID 35057861, 2022). "Therefore, we next analyzed the role of SLC3A2 in ferroptosis of laryngeal carcinoma." (PMID 35057861, 2022).
laryngeal carcinoma (continued). "Due to these functions, the overexpression of SLC3A2 and SLC7A11 is related to the occurrence and development of various types of cancer, including laryngeal carcinoma." (PMID 35057861, 2022).
schizophrenia (3 papers, 2017 to 2025). A major psychotic disorder characterized by abnormalities in the perception or expression of reality. "Research on the mRNA expression of SLC7A11 and SLC3A2 has revealed that diagnostic tools for schizophrenia in a clinical setting must be validated." (PMID 34575878, 2021). "Comprehensive and thorough studies can clarify whether all variants of SLC3A2 are related to schizophrenia’s pathophysiology and add to the current findings." (PMID 34575878, 2021). "To briefly conclude, we propose that system xc− subunits can serve as a diagnostic tool for schizophrenia based on the study of mRNA SLC7A11, and SLC3A2." (PMID 34575878, 2021). "The relationship between xc− and schizophrenia pathogenesis was investigated in a recent study, in which the mRNA expression of SLC7A11 and SLC3A2 in peripheral white blood cells was discovered to be lower in patients with schizophrenia than in healthy people." (PMID 34575878, 2021). "The peripheral mRNA expression levels of two system xc− subunits, SLC7A11 and SLC3A2 (particularly SLC3A2), are decreased in patients with schizophrenia." (PMID 34575878, 2021). "Compared with normal controls, a lower level of expression of SLC3A2 in peripheral white blood cell is shown in people with schizophrenia." (PMID 28280741, 2017). "According to the review of the literature, decreased mRNA expression of system xc− subunits SLC7A11 and SLC3A2 in patients with schizophrenia supports the hypoglutamatergic neurotransmission hypothesis regarding the pathogenesis of schizophrenia." (PMID 34575878, 2021). "From the perspective of the hypoglutamatergic hypothesis and experimental evidence, decreased mRNA expression levels of SLC7A11 and SLC3A2 in peripheral blood could be developed as accurate tools for diagnosing schizophrenia." (PMID 34575878, 2021). "Hence, the current review indicates an effective association and provides clear evidence that system xc− subunits SLC7A11 and SLC3A2 may serve as important biomarkers for schizophrenia." (PMID 34575878, 2021). "ERVW-1 transcripts significantly elevated in schizophrenia plasma (n=44) vs. controls (n=37) (p<0.05) by qRT-PCR, negatively correlated with reduced GPX4 and SLC3A2 (p<0.05), supporting ferroptosis role." (PMID 41200560, 2025). "We thus measured the mRNA expression levels of SLC3A2 and SLC7A11 in peripheral white blood cells in well-characterized, unrelated patients with schizophrenia and healthy controls." (PMID 34575878, 2021).
vitiligo (3 papers, 2022 to 2024). Generalized well circumscribed patches of leukoderma that are generally distributed over symmetric body locations and is due to autoimmune destruction of melanocytes. "In this study, we used bulk RNA-seq to verify that RBP genes are associated with vitiligo development in melanocytes and the function of SLC3A2 at the cellular level." (PMID 38438962, 2024). "Future studies should explore the underlying mechanism between SLC3A2 expression and the prognosis of vitiligo." (PMID 38438962, 2024). "We identified the RBP genes of different cell subsets in patients with vitiligo and confirmed that downregulating SLC3A2 can promote ferroptosis in melanocytes." (PMID 38438962, 2024). "Melanocyte-related RBPs were identified, and it was confirmed that SLC3A2 interference induced melanocyte ferroptosis, providing a new avenue for research on the pathogenesis of vitiligo." (PMID 38438962, 2024). "This study revealed that downregulating SLC3A2 can promote ferroptosis in melanocytes, offering new insights into the pathogenesis of vitiligo and potential therapeutic targets." (PMID 39430757, 2024). "Cell experiments were conducted to explore the role of the key RBP gene SLC3A2 in vitiligo." (PMID 38438962, 2024). "Therefore, this is the first study to demonstrate a relationship between ferroptosis and SLC3A2 expression in vitiligo melanocytes." (PMID 38438962, 2024). "Interestingly, IFN-γ exposure did not significantly reduce the expression of GPX4, SLC7A11, or SLC3A2, implying that other factors are involved in the increasing ferroptosis-sensitive state of melanocytes in patients with vitiligo." (PMID 35962439, 2022). "We identified the key RBP genes related to melanocytes in patients with vitiligo and confirmed that the RBP gene SLC3A2 promotes ferroptosis in melanocytes." (PMID 38438962, 2024). "In conclusion, understanding the role of ferroptosis in vitiligo and targeting key regulators such as GPX4 and SLC3A2 may lead to the development of novel treatments that could improve outcomes for patients with vitiligo." (PMID 39430757, 2024).
asthma (2 papers, 2022). "Consistently, the expression of SLC7A11, SLC3A2, and GPX-4 was also inhibited, while the level of ALOX5 was enhanced in lung tissues of asthma mice or IL-13-stimulated BEAS-2B cells, further demonstrating the initiation of ferroptosis during the development of asthma." (PMID 35154576, 2022).
COVID-19 (2 papers, 2021 to 2024). A disease caused by infection with severe acute respiratory syndrome coronavirus 2. "Regarding alleged imaging markers, SLC2A3 was abundant in macrophage subtypes enriched in severe COVID-19 patients, and we identified SLC3A2, SLC2A3, and FOLR2 as candidate molecules as imaging targets." (PMID 34239034, 2021). "SLC3A2 and SLC2A3 in the M01 cluster and FOLR2 in the M03 cluster were identified in results from both methods, indicating that [18F]FDG and [18F]-labeled folic acid derivatives may be useful for imaging severe COVID-19." (PMID 34239034, 2021).
endometrial carcinoma (2 papers, 2022 to 2025). A malignant tumor arising from the epithelium that lines the cavity of the uterine body. "Although there was no reports of OIP5-AS1 regulating SLC3A2/SLC7A5 in OA, study have demonstrated that in endometrial carcinoma cells, OIP5-AS1 can upregulate the expression of SLC7A5 by targeting miR-152-3p, thereby promoting cell proliferation." (PMID 40420260, 2025).
head and neck cancer (2 papers, 2021 to 2024). A primary or metastatic malignant neoplasm affecting the head and neck. "SLC3A2/CD98hc and two L-type amino acid transport binding partners, LAT1 and ascAT1 (derived from SLC7A5 and SLC7A10, respectively), were analyzed independently as prognostic markers in bladder, breast, cervical, lung, renal and head and neck cancers." (PMID 34112739, 2021).
Hyperglycemia (2 papers, 2024 to 2025). An increased concentration of glucose in the blood. "So, we found that STZ-induced diabetic mice developed classical DN features including hyperglycemia, albuminuria, and glomerular pathology while exhibiting reduced SLC3A2 expression and elevated iron accumulation in GECs—demonstrating ferroptosis activation during DN progression." (PMID 40703306, 2025).
Hyperphenylalaninemia (2 papers, 2020 to 2021). "This is because hyperphenylalaninemia competitively blocks the SLC7A5/SLC3A2 complex-mediated transport of thyroid hormones." (PMID 32874918, 2020).
hypertrophic cardiomyopathy (2 papers, 2024). A condition in which the myocardium is hypertrophied without an obvious cause. "This study revealed the potential relationship between disulfidptosis and hypertrophic cardiomyopathy and put forward a predictive model containing disulfidptosis-associated genes (DRGs) of GYS1, MYH10, PDMIL1, SLC3A2, CAPZB, showing excellent performance by SVM machine learning model." (PMID 39701955, 2024).
ischemic stroke (2 papers, 2025). A stroke disorder caused by obstruction of blood flow to the brain, due to thrombotic (local blood clot formation) or embolic (due to a blood clot or other material traveling from another site) event. "However, further investigations are needed to elucidate the specific mechanism by which SLC3A2 regulates ferroptosis in ischemic stroke." (PMID 40552324, 2025).